GLT8D2 (glycosyltransferase 8 domain containing 2)
Synonyms: FLJ31494
Tractability: Antibody: UniProt predicts a signal peptide or a membrane-spanning region. PROTAC: ubiquitination databases record sites on it.
Gene: Protein-coding gene on chromosome 12 (103,988,612 to 104,064,468, reverse strand). Ensembl gene ENSG00000120820.
Subcellular location: Membrane
Subcellular location (Human Protein Atlas): Golgi apparatus; Vesicles
Gene Ontology:
Molecular function: glycosyltransferase activity; UDP-glycosyltransferase activity
Cellular component: membrane
Genetic constraint (gnomAD): Loss-of-function variants: 22 observed, 23.6 expected, observed/expected ratio (o/e) 0.93, 90% interval 0.67 to 1.33. The upper end of that interval is the gene's LOEUF score, 1.33, which puts it in group 5 of 6, group 1 being the genes least tolerant of losing a copy. Missense variants: 259 observed, 315.06 expected, observed/expected ratio (o/e) 0.82, 90% interval 0.74 to 0.91. Synonymous variants: 102 observed, 113.97 expected, observed/expected ratio (o/e) 0.89, 90% interval 0.76 to 1.05.
Homologues: Orthologues: chimpanzee GLT8D2 (99% identical), macaque GLT8D2 (99% identical), rabbit GLT8D2 (95% identical), dog GLT8D2 (94% identical), pig GLT8D2 (94% identical), rat Glt8d2 (93% identical), mouse Glt8d2 (92% identical), guinea pig GLT8D2 (85% identical), tropical clawed frog glt8d2 (68% identical), zebrafish glt8d2 (60% identical). Paralogues in human: GLT8D1 (49% identical).
Diseases named in the same sentence as GLT8D2 in open-access papers:
GLT8D2 is named in the same sentence as 18 diseases in open-access papers, as found by Europe PMC text mining. Sharing a sentence is not in itself a finding about the gene and the disease. The quoted sentences say what the papers report.
non-alcoholic fatty liver disease (3 papers, 2021 to 2022). "GLT8D2 is a member of the glycosyltransferase eight family that contributes to the pathogenesis of non-alcoholic fatty liver disease by regulating the accumulation of triglycerides." (PMID 36685847, 2022). "GLT8D2 and MAN2A2 have been implicated in non-alcoholic fatty liver disease and coinfected liver disease, respectively." (PMID 33705408, 2021).
ovarian carcinoma (3 papers, 2021 to 2023). A malignant neoplasm originating from the surface ovarian epithelium. "Consistently, analysis of TCGA datasets showed that overexpression of GLT8D2 was significantly associated with ovarian cancer poor survival by Gene Set Enrichment Analysis (GSEA)." (PMID 34294681, 2021). "Glycosyltransferase GLT8D1 and GLT8D2 have been reported to be associated with head and neck squamous cell carcinoma, melanomas, glioma, GBM, and ovarian cancer chemoresistance." (PMID 37277853, 2023). "Herein, we found that overexpression of GLT8D2 confers CDDP resistance to ovarian cancer cells via activating the FGFR/PI3K/AKT signaling pathway." (PMID 34294681, 2021). "In our study, we found that the expression of Glycosyltransferase 8 domain containing 2 (GLT8D2) was significantly upregulated in ovarian cancer samples with CDDP (Cis-dichlorodiammine-platinum) resistance." (PMID 34294681, 2021). "Taken together, our results suggest that overexpression of GLT8D2 is involved in chemoresistance and correlates with progression and poor prognosis in human ovarian cancer." (PMID 34294681, 2021). "By using affinity purification/mass spectrometry (IP/MS) and reciprocal co-immunoprecipitation (co-IP) analyses, we found that GLT8D2 interacts with fibroblast growth factor receptor 1(FGFR1) in ovarian cancer cells." (PMID 34294681, 2021). "The chemoresistance effect of GLT8D2 in ovarian cancer cells was significantly inhibited by treatment with a FGFR inhibitor or AKT inhibitor (GDC-0068) (PMID: 23287563)." (PMID 34294681, 2021). "Colony formation assay show that overexpression of GLT8D2 significantly enhanced the anti-apoptosis ability compared with the vector control, however, inhibition of GLT8D2 in ovarian cancer cells reverse it." (PMID 34294681, 2021). "Gene Set Enrichment Analysis (GSEA) show that the mRNA levels of GLT8D2 expression in ovarian cancer not only correlation with the FGFR-activated gene signatures but also with PI3K/AKT-activated gene signatures in published datasets." (PMID 34294681, 2021). "GLT8D2 is a potential therapeutic target, which may enhance the sensitivity to platinum for ovarian cancer patients with chemoresistance." (PMID 37277853, 2023). "Importantly, pharmacological inhibition of FGFR and PI3K (phosphatidylinositol 3-kinase) signaling pathway significantly counteracted GLT8D2-induced chemoresistance and enhanced platinum’s therapeutic efficacy in ovarian cancer." (PMID 34294681, 2021). "Next, we investigated whether GLT8D2-mediated ovarian cancer chemoresistance occurs through FGFR/PI3K activation." (PMID 34294681, 2021). "Therefore, our findings suggest that GLT8D2 is a potential therapeutic target for the treatment of ovarian cancer." (PMID 34294681, 2021). "Interestingly, in our study we found that the anti-CCP effect of GLT8D2 in ovarian cancer cells was significantly inhibited by treatment with FGFR inhibitor (TAS-120) or AKT inhibitor (GDC-0068) by colony formation and Annexin V-FITC assay." (PMID 34294681, 2021). "Furthermore, GLT8D2 was also significantly increased in ovarian cancer and was positively correlated with shorter overall, relapse-free survival and post progression survival in ovarian cancer patients with platinum-based chemotherapy." (PMID 34294681, 2021). "Furthermore, compare to platinum sensitive tissues, the protein level of GLT8D2 was elevated in the ovarian cancer samples with platinum resistance by performing western blotting and IHC analyses." (PMID 34294681, 2021). "Importantly, pharmacological inhibit both FGFR and PI3K/AKT signaling significantly reversed GLT8D2-induced chemoresistance and enhanced platinum’s therapeutic efficacy in ovarian cancer." (PMID 34294681, 2021). "Furthermore, Annexin V assay show that the percentage of apoptotic cells in GLT8D2-overexpression ovarian cancer cells treated with CDDP was much lower compared than that in control cells, but much higher in GLT8D2-silenced cells." (PMID 34294681, 2021).
ovarian carcinoma (continued). "Interestingly, we found that GLT8D2 interacts with FGFR1 in ovarian cancer cells and activated FGFR signaling, subsequently activated the PI3K/AKT signaling pathway." (PMID 34294681, 2021). "Additionally, overexpression of GLT8D2 confers ovarian cancer to cisplatin (CDDP) resistance." (PMID 37277853, 2023). "Meanwhile, the clinical relevance of GLT8D2 expression and FGFR/PI3K activation was further characterized in human ovarian cancer." (PMID 34294681, 2021). "The correlation of GLT8D2 expression and XIAP, an important anti-apoptosis factor and downstream molecules of PI3K/AKT signalling, was further confirmed in clinical ovarian cancer samples with chemotherapy (r = 0.77, P < 0.05)." (PMID 34294681, 2021). "Therefore, our findings suggest that GLT8D2 is a potential therapeutic target for the treatment of ovarian cancer; targeting GLT8D2/FGFR/PI3K/AKT signaling axis may represent a promising strategy to enhance platinum response in patients with chemoresistant ovarian cancer." (PMID 34294681, 2021). "Cell viability assay show that overexpression of GLT8D2 enhanced CDDP resistance compared with the vector-transfected cells, however, inhibition of GLT8D2 in ovarian cancer cells were more sensitive to CDDP treatment than control-transfected cells." (PMID 34294681, 2021). "In order to explore the function of GLT8D2 in ovarian cancer chemoresistance, the in vivo subcutaneous inoculation models to assess the anti-CDDP effect of GLT8D2 in ovarian cancer." (PMID 34294681, 2021). "Biological experiment demonstrate that GLT8D2 overexpression confers CDDP resistance on ovarian cancer cells; however, inhibition of GLT8D2 sensitized ovarian cancer cell lines to CDDP cytotoxicity both in vitro and in vivo." (PMID 34294681, 2021). "Moreover, overexpression of GLT8D2 was associated with chemoresistance in human ovarian cancer, which show that 72.7% of GLT8D2-overexpression ovarian cancer samples cases exhibited chemoresistance, suggesting that GLT8D2-overexpression might be involved in ovarian cancer chemotherapy failure." (PMID 34294681, 2021). "In the current study we demonstrate that the expression of glycosyltransferase GLT8D2 was significantly upregulated in CDDP resistance-ovarian cancer samples and GLT8D2 confers CDDP resistance on ovarian cancer cells both in vitro and in vivo." (PMID 34294681, 2021). "Firstly, we found that the expression of GLT8D2, FRS2a (Tyr196), AKT (Ser473) and XIAP were significantly increase in six platinum resistant clinical ovarian cancer samples, compared with six platinum sensitive clinical ovarian cancer samples." (PMID 34294681, 2021). "Therefore, as a member of glycosyltransferases family proteins, it would be interesting to explore whether GLT8D2 enhanced cisplatin resistance in ovarian cancer via regulating mitochondrial oxidative phosphorylation or by regulating the levels of ROS, which will be carried out in our laboratory." (PMID 34294681, 2021). "Only one study implied that overexpression of GLT8D2 confers CDDP resistance to ovarian cancer via activating the FGFR/PI3K/AKT signaling pathway, and suggested that GLT8D2 is a potential therapeutic target for ovarian cancer to enhance platinum response in patients with chemoresistance." (PMID 37277853, 2023). "To investigate the chemoresistance role of GLT8D2 in ovarian cancer progression, we firstly examine the protein expression of GLT8D2 in ovarian cancer cell lines and OVCAR3 and SKOV3 cancer cell lines was chose for stably overexpressed and knockout GLT8D2 expression." (PMID 34294681, 2021). "GLT8D2 could contribute to FGFR/PI3K/AKT activation and induce chemoresistance in ovarian cancer." (PMID 36685847, 2022).
gastric cancer (2 papers, 2023 to 2024). A primary or metastatic malignant neoplasm involving the stomach. "Therefore, the analysis results indicate that DNA methylation patterns of GLT8D2 may play a role in the development and prognosis of gastric cancer." (PMID 37277853, 2023).
adenomyosis (1 paper, 2022). The growth of endometrial tissue inside the muscular wall of the uterine corpus. "In our study, the expression of GLT8D2 was downregulated in adenomyosis and positively correlated with the resting CD4 memory T-cell, resting NK cells and gamma-delta T-cell and negatively correlated with monocytes and CD8 T-cell." (PMID 36685847, 2022). "The microarray dataset analysis revealed that the expression levels of TMEM97, GLT8D2, NME5, STEAP1, and TOMM20 were significantly downregulated in the endometrium of women with adenomyosis compared with those in the control group (p < 0.05)." (PMID 36685847, 2022). "The expression levels of STEAP1, GLT8D2, NME5, and TOMM20 were downregulated and showed statistical significance (p < 0.05) in the adenomyosis group compared with those in the control group." (PMID 36685847, 2022). "This study identified STEAP1, TOMM20, GLT8D2, and NME5 as potential biomarkers for adenomyosis." (PMID 36685847, 2022).
chronic hepatitis C (1 paper, 2015). "European GWAS have identified SNPs in MERTK, GLT8D2, TULP1, and RNF7 as the genetic factors responsible for liver fibrosis progression in chronic hepatitis C during the natural course." (PMID 26352693, 2015).
leprosy (1 paper, 2017). Leprosy is a chronic infectious disease affecting primarily the skin and peripheral nervous system. "We found that five gene variants including gene GAL3ST4, CHGB48, CHGB23, GLT8D2 and ANKRD35 were more frequently reported than the other ten variants among the remaining six patients from two leprosy families by means of gene sequencing (data not shown)." (PMID 29180661, 2017).
steatosis (1 paper, 2015). Increased lipid within the cytoplasm of cells. "To elucidate the mechanism of the effect of GLT8D2 on hepatocyte steatosis, we next examined the expressions of proteins involved in lipid homeostasis after GLT8D2 overexpression or knockdown." (PMID 25952508, 2015). "In the in vitro study, we also found that GLT8D2 expression increased in steatosis HepG2 cells compared with normal HepG2 cells." (PMID 25952508, 2015). "GLT8D2 expression increased in steatosis HepG2 cells compared with that in normal HepG2 cells." (PMID 25952508, 2015). "In order to investigate whether GLT8D2 affected hepatocyte steatosis, HepG2 cells were transfected with his-GLT8D2 plasmid or GLT8D2 shRNA, respectively, and cultured continuously under non-fat-loading and fat-loading conditions." (PMID 25952508, 2015).
cancer (5 papers, 2018 to 2025). A tumor composed of atypical neoplastic, often pleomorphic cells that invade other tissues. "For example, Notch, Hedgehog, FGF, and TGFBR pathways correlated with GLT8D1, while GLT8D2 was significantly linked to PI3K-Akt signaling pathways, pathways in cancer, cell cycle checkpoints, and focal adhesion." (PMID 37277853, 2023). "Conversely, GLT8D2 expression presented a significantly lower level in more than half of cancer types (18 out of 33)." (PMID 37277853, 2023). "Our study found that GLT8D1/2 gene alterations occurred in multiple cancer types, among GC samples, GLT8D1 and GLT8D2 were altered in 3.64% and 1.59%, respectively." (PMID 37277853, 2023). "Unsupervised principal component analysis with the main cancer invasiveness-enriched genes (ASPN, GLT8D2, OLFML2B, CRISPLD2, ADAM12, POSTN, and PRRX1) allowed for the discrimination of subgroups of BMAL1-dependent CRC patients (p = 9.9 × 10−4)." (PMID 34065633, 2021). "Overexpression of GLT8D2 significantly enhanced, whereas silencing of GLT8D2 reduced, the activity of FOXO luciferase reporter activity in OVCAR-3 and SKOV3 cancer cells." (PMID 34294681, 2021). "Finally, four novel enzymes with unappreciated biological functions in cancer were identified, namely thromboxane A synthase 1 (TBXAS1), 5′,3′‐nucleotidase, cytosolic (NT5C), glycosyltransferase 8 domain containing 2 (GLT8D2) and reticulon 4 interacting protein 1 (RTN4IP1)." (PMID 39757767, 2025).
tumor (4 papers, 2021 to 2024). "We found that these glycosylation-related genes revealed a robust correlation with the abundance of Tumor Infiltrating Lymphocytes (TILs), especially the GLT8D2 which is associated with many TILs." (PMID 38840920, 2024). "Our findings implied that GLT8D1/2 genes may affect the prognosis of GC patients through tumor immunity, especially GLT8D2." (PMID 37277853, 2023). "Considering the results above, our study suggested that GLT8D1/2 may affect the prognosis of GC patients through tumor immunity, especially GLT8D2." (PMID 37277853, 2023). "Together, GLT8D2 may affect GC development and prognosis by multiple immune cells infiltration, which require further investigation due to complex immunomodulation mechanisms of anti-tumor immune response and immunosuppression." (PMID 37277853, 2023). "The results showed that the expression of IPCEF1, TFF3, GLT8D2, TPO and DIO1 were downregulated in the tumor group and DPP4, LRP4, CDH3, KCNJ2, CLDN1, GABRB2, FN1 were upregulated in the tumor group." (PMID 39513122, 2024). "Compare to the vehicle treatment, GLT8D2-shRNA plus CDDP treatment resulted in a significantly reduction in tumor growth and tumor weight compared with that in the control group." (PMID 34294681, 2021). "Interestingly, GLT8D2 expression was also found to have a broad positive correlation with the infiltration of iDCs, pDCs, DCs, and TReg cells, which indicate that GLT8D2 may play a crucial role in promoting immune cell infiltration within the tumor microenvironment." (PMID 37277853, 2023).
GLT8D2 also shares sentences with these, for which no sentence is quoted: breast carcinoma (1 paper); fatty liver disease (1); glioma (1); head and neck squamous cell carcinoma (1); hepatocellular carcinoma (1); liver disease (1); liver fibrosis (1); melanoma (1); mucopolysaccharidoses (1).